FSCN1 (fascin actin-bundling protein 1)
Diseases named in the same sentence as FSCN1 in open-access papers (continued):
Sharing a sentence is not in itself a finding about the gene and the disease.
tumor (continued). "These HLA-A24 ligands were possibly overexpressed in tumor samples and were therefore chosen as nonmutated TAA candidates of CRC111, which comprised peptides encoded by the KLK8, DEFA3, STRIP2, MMP1, FSCN1, TBX15, and PHLDA1 genes." (PMID 34185709, 2021). "This behavior might be explained by a reduction in the active release of FSCN1 from the primary mass after its removal, which might characterize advanced ACC, followed by a return to the pre-surgery levels once the tumor progresses or relapses." (PMID 34248854, 2021). "In vitro experiments showed that FSCN1 silencing sensitized tumor cells with PIK3CA alterations, but not cells with wild-type PIK3CA to IR." (PMID 34249689, 2021). "To investigate the clinical significance of LINC00152 and FSCN1 in CRC specimens, we examined LINC00152 and FSCN1 expression levels by analyzing tissue microarray containing 30 cases normal colorectal mucosa tissues and 94 CRC tumor tissues." (PMID 32042551, 2020). "Among them, 13 proteins correlated with clinicopathological parameters and of these proteins, eight proteins were identified in neoplastic islands (ACTR2, CSTB, COL1A2, LTA4H, PGK1, NDRG1, S100A8, S100A9) and five proteins were identified in tumor stroma (COL6A1, FSCN1, ITGAV, MB, THBS2)." (PMID 30185791, 2018). "Our findings demonstrated that miR-145 function as a tumor suppressor in NPC development and progression through targeting FSCN1, suggesting that miR-145/FSCN1 pathway may sever as a potential novel therapeutic target for patients with NPC." (PMID 25816323, 2015). "Our findings demonstrated that miR-145 function as a tumor suppressor in NPC development and progression via targeting FSCN1, which could sever as a potential novel therapeutic target for patients with NPC." (PMID 25816323, 2015). "Immunohistochemistry revealed that FSCN1 was markedly expressed in the tumour lesion, whereas no expression was observed in adjacent tissues including the smooth muscle layers." (PMID 20160723, 2010). "We are not aware of similar findings obtained concerning tumor cells treated with Fscn1 inhibitors." (PMID 35681718, 2022). "In our analysis, we found a positive correlation between Pre-S serum FSCN1 levels and stage, as well as a negative relationship with the DFS time, reflecting our previous findings that FSCN1 expression in the tumor mass is associated with disease progression and worse prognosis." (PMID 34248854, 2021). "Additionally, FSCN1 may regulate nuclear factor-κB (NF-κB) activity, and the expression of MMP-2 and MMP-9, to promote tumor invasion and migration." (PMID 32699531, 2020). "Moreover, FSCN1 expression, absent in primary PCa, is detected in NEPC tumours and may be involved in tumour progression." (PMID 37875732, 2023).
cancer (102 papers, 2009 to 2025). A tumor composed of atypical neoplastic, often pleomorphic cells that invade other tissues. "By using this endpoint, high pretreatment FSCN1 serum levels proved to be associated with shorter cancer-specific survival both in the univariable and multivariable analyses." (PMID 37634036, 2024). "Overexpression of FSCN1, which promotes cell migration, has been reported to be associated with cancer metastasis in many studies." (PMID 37491232, 2023). "Fascin actin-bundling protein 1 (FSCN1) was implicated in an increased risk of metastasis in various human cancers." (PMID 35454025, 2022). "Both studies indicate FSCN1-induced invasion in cancer cells due to loss of cell-to-matrix adhesion." (PMID 34830909, 2021). "By contrast, FSCN1 overexpression in cancer cells is associated with E-cadherin downregulation and promotion of epithelial-mesenchymal transition (EMT)." (PMID 34494554, 2021). "This is associated with the different types of FSCN1-mediated signaling pathways that are involved in the malignant properties of cancer cells." (PMID 33614909, 2021). "In this study, we show that in the context of PIK3CA mutation or amplification, high expression of fascin actin-bundling protein 1 (FSCN1) (using the median as the cut-off value) is associated with poor prognosis and radiotherapy response in cancer patients." (PMID 34249689, 2021). "Clinical IHC studies showed that in nearly all cancers, FSCN1 expression is associated with aggressive clinical course, metastatic progression, and poor prognosis." (PMID 33614909, 2021). "After that, a series of studies has shown that FSCN1 is highly expressed in different cancer types and that its expression is associated with aggressive clinical course, poor prognosis, and shorter survival outcomes." (PMID 33614909, 2021). "Cancer-associated lncRNAs compete endogenous RNA (ceRNA) in the regulation of FSCN1 expression through miRNAs." (PMID 33614909, 2021). "The expression of FSCN1 is associated with an aggressive clinical course and poor outcomes in different cancer types." (PMID 33614909, 2021). "McGuire and colleagues showed that the silencing of FSCN1 in ovarian cell lines (HeyA8, Ovcar5, and Tyk-nu), primary human cancer-associated fibroblasts and primary human omental mesothelial cells reduced metastasis." (PMID 34830909, 2021). "Although FSCN1 overexpression has been extensively reported in different human cancers, molecular mechanisms underlying FSCN1 upregulation during malignant transformation and metastatic progression are under-studied areas." (PMID 33614909, 2021). "Although several studies have indicated a potential diagnostic utility of FSCN1, its therapeutic role as an anti-cancer target is still under investigation." (PMID 34830909, 2021). "On the other hand, loss of miRNAs -133a and -145 was found to enhance FSCN1 expression, thus stimulating cancer cell growth, proliferation, migration, and invasion along with the inhibition of apoptosis." (PMID 34830909, 2021). "In the context of PIK3CA mutation or amplification, high expression of FSCN1 is associated with poor prognosis and radiotherapy response in cancer patients; mutant PIK3CA (E542K and E545K) can enhance glucose metabolism and cell proliferation in cancer cells." (PMID 35069968, 2021). "Several additional investigations also reported the role of FSCN1 in other types of cancer and its association with an aggressive phenotype, poor prognosis, and short survival." (PMID 34830909, 2021). "In a total of 26 IHC studies of 5 prevalent human carcinomas when identified for meta-analysis found FSCN1 was associated with increased risk of mortality for breast and oesophageal carcinomas." (PMID 33739025, 2021). "Overexpression of FSCN1 promotes migration and invasion of cancer cells, and is associated with clinically unfavorable phenotypes in human epithelial cancers including EOC." (PMID 28881818, 2017).
cancer (continued). "Several studies have reported that FSCN1 is highly expressed in malignant tumors, and is associated with increased cell motility and aggressive behavior of tumors." (PMID 28186968, 2017). "Studies also reported that FSCN1 is upregulated in malignant tumors, and is associated with the aggressive behavior of tumors by promoting cell invasiveness." (PMID 25816323, 2015). "In solid cancers, FSCN1 has been mainly associated with cancer cells and its stromal expression has been generally overlooked." (PMID 25485970, 2014). "Elevated levels of validated miR-133b targets such as CXCR4, FGFR1, FSCN1 has been associated with prognosis of various cancers." (PMID 24967583, 2014). "Inhibiting histone H3 phosphorylation, causing nuclear FSCN1 accumulation and actin filament assembly, may explain the anti-cancer properties of nuclear FSCN1." (PMID 39055653, 2024). "Importantly, FSCN1 overexpression has been strongly associated with poor prognosis and metastatic progression across different cancer types." (PMID 37875732, 2023). "FSCN1 was also reported to be associated with high-risk HPV to enhance cancer progression." (PMID 34830909, 2021). "Recently, FSCN1 has received a lot of attention, because multiple studies have implicated it as a candidate biomarker or therapeutic target for aggressive, metastatic carcinomas of many cancer types." (PMID 33614909, 2021). "FSCN1, which has been closely associated with lung and other cancers, was chosen for further study." (PMID 32493389, 2020). "Emerging evidence indicates that Fascin-1 (FSCN1) may possess a causal role in the development of several types of cancers and serves as a novel biomarker of aggressiveness in certain carcinomas." (PMID 29142206, 2017). "FSCN1 is an endothelial cell biomarker that also identifies differentiated luminal and spindle-like cells in normal breast tissue, and which has been extensively linked to the metastatic potential of cancer cells." (PMID 26167915, 2015). "Inhibition of FSCN1 using anticancer drugs has shown potential for cancer treatment and clinical applications, making it a promising therapeutic target for various cancer types." (PMID 40818124, 2025). "Key genes (ACTIN1, LIMK1, CORO1C, INF2, SH3D21, CFL1, FSCN1, MYO1B) implicated in actin cytoskeleton organization were identified, suggesting their role in oral potentially malignant disorders and cancer progression." (PMID 40818124, 2025). "Nuclear FSCN1 exerts anti-cancer effects through actin bundling for chromatin organization and efficient DNA repair." (PMID 39055653, 2024). "Of these genes, FSCN1 was upregulated across all cancer types as compared to normal tissues, whereas ITGA5 and TGM2 were only upregulated in 70% of the tumors." (PMID 36978029, 2023). "It has been shown that FSCN1 expression correlates with poor clinical outcomes and shorter survival across different cancer types." (PMID 37875732, 2023). "Previous reports have suggested the role of FSCN1 in the acquisition of chemoresistance in human cancers, such as paclitaxel, doxorubicin, and gefitinib resistance." (PMID 37596693, 2023). "Here, we found that high expression of FSCN1 and ITGA5 is associated with impaired survival in more than ten cancers, and high expression of TGM2 is also associated with poor prognosis in more than five cancers." (PMID 36978029, 2023). "Systematic reviews and meta-analyses have revealed that FSCN1 overexpression promotes metastasis and mortality in various tumors, suggesting that FSCN1 can be a therapeutic target for cancer." (PMID 38077434, 2023). "By increasing membrane protrusions (filopodia and invadopodia), facilitating focal adhesion turnover and regulating nuclear organisation, FSCN1 promotes the physical translocation of metastatic cancer cells." (PMID 37875732, 2023). "FSCN1 is an actin-bundling protein that is involved in cancer metastasis and recurrence through the regulation of cellular proliferation and cloning efficiency." (PMID 35602576, 2022).
cancer (continued). "Knockdown of FSCN1 can inhibit the growth of CaSki cancer cells and reduce tumorigenicity in nude mice by regulating the expression of PCNA, survivin, CDK4 and p21." (PMID 35178306, 2022). "FSCN1 is markedly increased in diverse cancers and affects various cellular processes, such as invasion, EMT, metastasis, as well as drug resistance." (PMID 35055115, 2022). "Alternatively, some studies have explored the possible mechanisms by which FSCN1 affects the occurrence and development of cancer." (PMID 35178306, 2022). "In this review, we discuss, at length, the structure and biological function of FSCN1, and describe the expression patterns, biological processes, and regulatory mechanisms of FSCN1 in various cancers." (PMID 35711849, 2022). "The prognostic value of FSCN1 expression has been demonstrated in several cancer types, and its upregulation is considered to promote migration and invasion." (PMID 35401239, 2022). "On the one hand, a large number of studies have reported the regulatory mechanisms mediating abnormal expression of FSCN1 in cancer." (PMID 35178306, 2022). "The regulatory relationship between exosomal lncRNAs and cancer cell malignancy by regulating FSCN1 has been demonstrated." (PMID 36591473, 2022). "In vitro and in vivo studies have been performed in cancer cell lines using FSCN1 depletion or overexpression." (PMID 33614909, 2021). "The regulation of FSCN1 expression in cancers is challenging and is affected by both transcriptional and post-transcriptional mechanisms." (PMID 33614909, 2021). "This review provides a brief overview of the FSCN1 role in various cancers with emphasis on gynecological malignancies." (PMID 34830909, 2021). "This review summarizes not only the role of FSCN1 in cancers but also its clinical application in cancer therapy by targeting FSCN1." (PMID 33614909, 2021). "In the last 20 years, various clinical studies have documented that FSCN1 is a novel biomarker candidate for aggressive carcinomas of many cancer types." (PMID 33614909, 2021). "FSCN1 has recently been shown to promote cancer cell migration and invasion through its role in formation of cellular protrusions such as filopodia and invadopodia." (PMID 35069968, 2021). "Varying the expression levels of FSCN1 reversed EMT in many different cancer cells, as exhibited by corresponding changes in the expression of epithelial and mesenchymal markers." (PMID 33614909, 2021). "Different regulatory factors and signaling pathways regulate FSCN1 expression by activating TFs in different cancer cell types." (PMID 33614909, 2021). "FSCN1 has been shown to be unusually expressed in transformed epithelial cells and many human cancers." (PMID 33614909, 2021). "Since FSCN1 can stimulate cancer cell migration and metastasis, there are several limitations in developing therapeutic targets against FSCN1." (PMID 34830909, 2021). "FSCN1 also regulates cell-cell adhesions in cancer cells, where it directly binds to microtubules (MT), regulating MT dynamics and adhesion stability during cell migration." (PMID 34494554, 2021). "On the other hand, one of the principal functions of FSCN1 contributions to cancer progression is the actin-bundling function." (PMID 34830909, 2021). "Up-to-date studies on FSCN1 as a novel biomarker and therapeutic target for human cancers are reviewed." (PMID 33614909, 2021). "Elevated FSCN1 levels have been reported in many types of human cancers and have been correlated with aggressive clinical progression, poor prognosis, and survival outcomes." (PMID 33614909, 2021). "Due to the ability of FSCN1 to induce cell migration, invasion, and metastasis, FSCN1 is a potential candidate molecule for anti-cancer or anti-metastatic therapy in human cancers." (PMID 34830909, 2021). "In our study, we found LINC01711 regulated the expression of FSCN1 through targeting miR-326 in TE-1 cells, which provided deeper insights into the mechanism of FSCN1 on cancer cells." (PMID 34370713, 2021).
cancer (continued). "For example, FSCN1 is important for cancer cell stemness, extracellular vesicle release, chemoresistance, and anoikis resistance, yet the mechanisms involved are largely unclear." (PMID 33614909, 2021). "Evidence shows that FSCN1 is a viable novel target molecule for anti-cancer or anti-metastatic therapy in multiple human cancers." (PMID 33614909, 2021). "The study suggested that Wnt/β-catenin signaling regulates epithelial-mesenchymal transition (EMT) induced by FSCN1 in LMP1-positive cancers to provoke cancer progression." (PMID 34830909, 2021). "The aim of these studies was to explore or evaluate the potential of FSCN1 as a biomarker (e.g., the studies in gastric and liver cancer)." (PMID 33614909, 2021). "Currently, FSCN1 is recognized as a candidate biomarker for multiple cancer types and as a potential therapeutic target." (PMID 33614909, 2021). "documented that Ser274 can be phosphorylated to modulate the actin-bundling capacity of FSCN1 in human cancer cells." (PMID 33614909, 2021). "Several studies have been aimed at understanding the molecular basis for elevated FSCN1 protein expression levels in human cancers." (PMID 33614909, 2021). "The main focus was on the role of FSCN1 and its upregulatory mechanisms and significance in cancer cells." (PMID 33614909, 2021). "Elucidation of FSCN1 regulatory mechanisms in certain cancer types is important for the development of targeted therapeutic agents." (PMID 33614909, 2021). "Cox regression analysis revealed that FSCN1 is an independent poor prognostic marker for many different human cancers." (PMID 33614909, 2021). "Studies are aimed at developing novel agents that can interfere with key FSCN1 functions in cancers." (PMID 33614909, 2021). "The decrease of the level of FSCN1 using synthetic siRNA or vector-based shRNA inhibits in vitro cell growth in many human cancer cell lines." (PMID 33614909, 2021). "The results showed that FSCN1 knockdown significantly decreased the growth of these cancer cells under IR treatment except for si-1 transfection in HeLa cells." (PMID 34249689, 2021). "FSCN1 is highly upregulated, both at the mRNA and protein level, in various human cancer cell lines." (PMID 33614909, 2021). "In conclusion, FSCN1 is highly upregulated in a variety of human cancers and functionally contributes toward cancer progression." (PMID 33614909, 2021). "The overexpression of FSCN1 in many other human cancers and their correlation with malignant properties have elucidated the important role of FSCN1 in cancer progression and prognosis." (PMID 33614909, 2021). "In nearly all cancers, the positive expression rate of FSCN1 was increased in cancer tissues compared to that in normal epithelium or para-carcinoma tissues." (PMID 33614909, 2021). "To confirm the potential of FSCN1 as a predictor for prognosis in cancer patients, we also performed ROC analysis." (PMID 34249689, 2021). "The available evidence is insufficient to assess the value of FSCN1 as a new driver gene in several cancer cell lines." (PMID 33614909, 2021). "Although the upregulation of FSCN1 has been extensively studied in many different cancer cells—several regulatory factors or signaling pathways regulate FSCN1 expression—their underlying mechanisms have not been established." (PMID 33614909, 2021). "Various cancer-related cellular properties, such as growth, migration, invasion, metastasis, and drug resistance, are affected by the forced changes in FSCN1 expression." (PMID 33614909, 2021). "Overexpression of FSCN1 in cancer cells leads to downregulation of E-cadherin and upregulation of EMT-promoting genes." (PMID 34494554, 2021). "There are several functions by which FSCN1 promotes cancer progression via inducing cancer cell growth, proliferation, migration, invasion, and metastasis." (PMID 34830909, 2021).